CCNE1 (cyclin E1)
Diseases named in the same sentence as CCNE1 in open-access papers (continued):
Sharing a sentence is not in itself a finding about the gene and the disease.
gastric cancer (continued). "Therefore, Bcl-2 and CCNE1 might contribute to the tumor promoting role of the NUDT21/SGPP2 pathway in gastric cancer cells." (PMID 34660260, 2021). "Gentiopicroside affects the expression of CCNE1, p-P38, CCND1, and p-AKT at the protein level, thereby exerting its anti-gastric cancer effect." (PMID 39086391, 2024). "Importantly, we found that CCNE1 amplification may have therapeutic relevance in gastric cancer." (PMID 38717153, 2024). "BD inhibited gastric cancer cell growth and proliferation through the LINC01667/miR-138-5p/Cyclin E1 pathway and induced cell cycle arrest in the s phase of gastric cancer cells." (PMID 38371913, 2023). "Since we have showed that Cyclin E1, an important cell cycle regulator, was significantly decreased after BD treatment, we thought that Cyclin E1, one of the potential target genes of miR-138-5p, might be the probable mechanism for regulating cell proliferation in gastric cancer." (PMID 33390953, 2020). "CCNE1 amplifications were recently reported in ATC and they are known to occur in multiple malignancies, including ovarian, breast, and gastric cancer." (PMID 30909364, 2019). "Morusin markedly inhibited gastric cancer cell proliferation by down-regulating CDKs and Cyclins, such as CDK2, CDK4, Cyclin D1 and Cyclin E1." (PMID 28915664, 2017). "While we observed impaired survival after trastuzumab in CCNE1-amplified gastric cancer compared with nonamplified gastric adenocarcinoma, surprisingly, we noted a trend toward improved survival after initiation of immunotherapy." (PMID 38717153, 2024). "Interestingly, we did not observe any differences in T-cell abundance in CCNE1-amplified gastric cancer from transcriptomic analysis." (PMID 38717153, 2024). "In addition, in a phase II trial of chemotherapy plus the HER2 inhibitor lapatinib for gastric cancer, nonresponders were enriched for CCNE1 amplification." (PMID 38717153, 2024).
osteosarcoma (35 papers, 2012 to 2025). A usually aggressive malignant bone-forming mesenchymal neoplasm, predominantly affecting adolescents and young adults. "In this study, we identified a cytoplasmic, low molecular weight cyclin E1 isoform (LMW-cyclin E1) in osteosarcoma that is significantly associated with poor patient outcomes." (PMID 40959067, 2025). "CCNE1, a critical regulator of the G1/S cell cycle transition, has been previously linked to increased disease severity, poor prognosis, and reduced chemotherapy response in osteosarcoma." (PMID 40710368, 2025). "To further investigate the cyclin E1 regulation mechanism, we first used immunofluorescence and immunohistochemistry staining to analyze cyclin E1 expression and distribution in osteosarcoma cells and 69 osteosarcoma lesions in situ." (PMID 40959067, 2025). "LMW-cyclin E1 was more strongly associated with poor prognosis of osteosarcoma patients than FL-cyclin E1, further demonstrating the critical role of LMW-cyclin E1 in promoting malignant biological behavior." (PMID 40959067, 2025). "In our previous study, we found that cyclin E1 was significantly overexpressed in osteosarcoma, and its expression was positively correlated with disease status and inversely correlated with prognosis and chemotherapeutic response." (PMID 40959067, 2025). "The Westernblot results further confirmed that palmatine reduces RRM2 expressionin both osteosarcoma cells and HVECs and decreases the expressionof cell cycle and DNA damage repair-related proteins, such as cyclinB1, cyclin E1, and CHEK1." (PMID 40834268, 2025). "Our results suggest that ELA2 is naturally present in OS cells at low levels, and upregulated ELA2 in osteosarcoma accelerates LMW-cyclin E1 formation." (PMID 40959067, 2025). "According to the cyclin E1 staining intensity in osteosarcoma tissue microarray, four staining patterns (staining score = 0, 1+, 2+, 3+) were defined separately for the cellular nucleus and cellular cytoplasm." (PMID 40959067, 2025). "A study investigating if inhibiting the Notch pathway prevents osteosarcoma growth demonstrated that a γ-secretase inhibitor attenuated the cyclin D1, cyclin E1, E2, and SKP2 expression." (PMID 36012128, 2022). "It was observed that the elevation of miR-874-3p inhibits CCNE1 expression in osteosarcoma, which led to G1/S arrest." (PMID 33123872, 2021). "CCNE1 amplification or cyclin E1 overexpression has also been described in a number of other cancers including osteosarcoma, breast, and non-small-cell lung cancer." (PMID 30472117, 2019). "The inhibition of Notch signaling in an osteosarcoma cell line resulted in reduced Cyclin E1, Cyclin E2, and Cyclin D mRNA expression." (PMID 28860516, 2017). "SMO has been identified as a potential drug target in osteosarcoma, as its inhibitor cyclopamine promotes G1 arrests and represses expression of cyclin D1, cyclin E1, SKP2, and pRb." (PMID 23251412, 2012). "We have previously reported that cyclin E1 is significantly overexpressed in osteosarcoma, that its expression is correlated with osteosarcoma progression, and that it can serve as a prognostic biomarker for osteosarcoma." (PMID 40959067, 2025). "Considering the high heterogeneity of osteosarcoma, the calpain family may act as upstream regulators of cyclin E1." (PMID 40959067, 2025). "Overall, our data show that the regulation of LMW-cyclin E1 is driven by neutrophil elastase in osteosarcoma, and the crosstalk between osteosarcoma cells and neutrophils may offer a novel therapeutic strategy." (PMID 40959067, 2025). "Thus, in this study, we first revealed that LMW-cyclin E1 isoforms are expressed and localized in the cytoplasm of osteosarcoma using a series of assays." (PMID 40959067, 2025).
osteosarcoma (continued). "The expression of cyclin E1 in osteosarcoma samples was further investigated using a Western blot assay, and the results revealed that, in addition to FL-cyclin E1 in OS, which was shown at 47 kDa, several distinct low molecular weight protein bands were also observed at 33–47 kDa." (PMID 40959067, 2025). "We previously reported that cyclin E1 is upregulated in osteosarcoma." (PMID 40959067, 2025). "In addition to CCND3 amplifications, amplifications of CCNE1 are common in osteosarcoma as well and the effect of CDK2 inhibition on tumor growth has been demonstrated by dinaciclib (SCH 727965) using patient‐derived xenografts." (PMID 33963544, 2021). "In osteosarcoma miR-874-3p was down-regulated leading to cyclin E1 increased expression." (PMID 33123872, 2021). "However, whether LMW-cyclin E1 is present in osteosarcoma remains unclear." (PMID 40959067, 2025). "In particular, CNV was more frequent in CCND3, AURKB, CCNE1, GID4, and MYC in P-AYA, while MDM2, CDKN2A/B, and FRS2 were more frequently altered in adult osteosarcoma (p < 0.001)." (PMID 35705558, 2022). "For instance, circ-0001721 accelerates the development of osteosarcoma via the miR-372-3p/MAPK7 axis, and circRNA circAGFG1 accelerates the progression of triple-negative breast cancer via regulating CCNE1, the sponge of miR-195-5p." (PMID 34568335, 2021). "To investigate the underlying molecular mechanism of baicalein on cell cycle regulation, we examined the expression levels of Cyclin D1, Cyclin E1, CDK4, CDK6, c-myc, pRb, p21 and p27 in osteosarcoma cells, which treated with different doses of baicalein." (PMID 29156780, 2017). "Moreover, several molecular markers for osteosarcoma have also been discovered, including MYC, Cyclin E1, and MiR-455-3p, which are all considered to be promising therapeutic targets." (PMID 33858425, 2021). "Our findings indicate that amplification of the MYC oncogene is a major driver of childhood osteosarcoma, while CCNE1 appears recurrently amplified independent of age." (PMID 33969640, 2021). "The inhibitory effects of ML264 on osteosarcoma cells are likely mediated via inhibition of JAK2 and STAT3 phosphorylation, decrease in β‐catenin and Runx2 levels, down‐regulation of cyclin D1, cyclin E1, CDK4, N‐cadherin, vimentin, Snail and MMPs expression, and up‐regulation of E‐cadherin levels." (PMID 32285603, 2020). "MicroRNA-874-mediated inhibition of the major G1/S phase cyclin, cyclin E1 (CCNE1) does not occur in osteosarcomas." (PMID 33028884, 2020). "This particular amplification was reported in 27% of osteosarcomas (6/22) in one study, and was directly correlated with increased cyclin E1 expression, but it does not correspond with chemotherapy response rates." (PMID 26510912, 2015). "However, the discrepant effects on osteosarcoma patients’ prognosis between CCNE1 and cyclin E1 protein indicated that there may be a hyperactive subtype of cyclin E1." (PMID 40959067, 2025). "Further evidence of DIC’s pro-tumorigenic role has been demonstrated in osteosarcoma, where DIC KO significantly reduces the expression of cyclin E1 (CCNE1) and increases its upstream regulators p21 and p27, suggesting that the DIC–p21/p27–CCNE1 axis plays a role in cell cycle regulation." (PMID 39795950, 2024). "Consistent with the mouse 45Ca osteosarcoma cell lines, cilia frequency and expression of CDK1, CCNE1 and CDC6 did not correlate with CDKN2A deletion." (PMID 37845394, 2023). "We reanalysed copy number readouts of 258 cases of high‐grade osteosarcoma from three different cohorts and identified a significant enrichment of focal MYC, but not CCNE1, amplifications in children." (PMID 33969640, 2021).
glioma (34 papers, 2010 to 2026). A benign or malignant brain and spinal cord tumor that arises from glial cells (astrocytes, oligodendrocytes, ependymal cells). "Interestingly, MicroRNAs such as miR-195 act as tumor suppressors by directly targeting CCNE1, which encodes Cyclin E1, thereby reversing chemoresistance in glioma." (PMID 41368202, 2026). "Thus, the CBX7-induced suppression of CCNE1, which encodes cyclin E1, contributed to the attenuation of glioma progression." (PMID 28460453, 2017). "We have analyzed the level of Reg-2 and its newly identified targets that encode the cyclins CCND1, CCNE1, CCNE2, CCNB1, CCNA2, and the kinases PLK1 and AURKA in glioma tumors." (PMID 38238463, 2024). "Our results demonstrated that the protein expression of Cyclin E1 and Cyclin D1 were obviously decreased, while the protein expression of P21 and P27 were significantly increased in glioma cells treated with NPS‐2143." (PMID 38509759, 2024). "The mechanisms involved in the suppression of glioma cell growth were blockage of the cell cycle in S phase by inhibition of CDK2/cyclin E1 and promotion of apoptosis through the Bcl-2/Bax pathway." (PMID 33116114, 2020). "Studies have also shown that in human gliomas, expression of FBXW7β mRNA is specifically suppressed and plays a key role in the pathogenesis of glioma with increased expression of CCNE1, Myc, and AURKA." (PMID 30791487, 2019). "The low-levels of intracellular miR-16 result in increasing Cyclin D1 and Cyclin E1 expression, and subsequently promoting glioma cells proliferation in vitro and in vivo." (PMID 29044221, 2017). "To test the correlations between URGCP and Cyclin D1 and Cyclin E1 expression in glioma, we first performed western blotting and found that the levels of Cyclin D1 and Cyclin E1 protein were upregulated in glioma tissues compared to normal tissues." (PMID 29044221, 2017). "Our study also demonstrated that c-myc acts as a transcriptional repressor to inhibit miR-16 expression in glioma, and the low-levels of intracellular miR-16 results in glioma growth through increasing Cyclin D1 and Cyclin E1 expression." (PMID 29044221, 2017). "And, more remarkable, URGCP also regulated the mRNA levels of Cyclin D1 and Cyclin E1 in glioma, suggesting that the transcriptional regulation is involved in this process, and the underlying mechanisms need further investigation." (PMID 29044221, 2017). "Taken together, these results suggest that both Cyclin D1 and Cyclin E1 downregulations contribute to miR-195-induced glioma cell growth arrest." (PMID 23383003, 2013). "To further investigate the role of Cyclin D1 and Cyclin E1 repression in miR-195-induced glioma cell growth arrest, we first examined the effects of Cyclin D1 and Cyclin E1 re-introduction on glioma cell proliferation." (PMID 23383003, 2013). "We demonstrated that miR-195 promotes glioma cell proliferation by directly targeting the 3′-UTRs of cyclin D1 and cyclin E1, consequently reducing phosphorylation of pRb and downregulating the proliferative marker PCNA." (PMID 23383003, 2013). "Taken together, our results suggest that miR-195 inhibit glioma proliferation both in vitro and in vivo by repressing Cyclin D1 and Cyclin E1 expression." (PMID 23383003, 2013). "miR-15b has been identified as an inhibitor of glioma growth while cyclin E1 has been found as a target of miR-15b, suggesting its role in cell cycle regulation." (PMID 23358700, 2013). "MiR-195 levels in 10 freshly collected glioma samples inversely correlated with the expression of Cyclin D1 (r = −0.709, P = 0.022), and Cyclin E1 (r = −0.783, P = 0.002)." (PMID 23383003, 2013). "Taken together, our results suggest that miR-195 plays an important role to inhibit the proliferation of glioma cells, and present a novel mechanism for direct miRNA-mediated suppression of cyclin D1 and cyclin E1 in glioma." (PMID 23383003, 2013).
glioma (continued). "This miRNA was recently shown to regulate cell cycle progression in glioma cells by targeting cell cycle-related genes, such as CCNE1." (PMID 20465802, 2010). "RIPK1 was positively correlated with the expression of cyclin E1 (CCNE1), CDK2, TIMP1, N-cadherin (CHD2), and other genes implicated in glioma proliferation and invasion, whereas MLKL exhibited a weaker or negative correlation with most genes in this signature." (PMID 41429922, 2025). "Similarly, CCNE1 deletions in gliomas were also correlated with a better outcome, which was similar with our result." (PMID 36439461, 2022). "NF‐κB regulates cyclin D1 and cyclin E1 expression to regulate glioma cell growth and invasion." (PMID 35945910, 2022). "Flow cytometry data showed that the knockdown of SIPA1 in A172 cells arrested cell cycle progression in the G1 phase, which was further supported by the downregulation of cell cycle proteins Cyclin A2, Cyclin D1 and Cyclin E1 in glioma cells with SIPA1 knockdown." (PMID 35431649, 2022). "Also, the novel lncRNA MIR497HG considered new tumor suppressors and prognostic biomarkers in glioma and significantly inhibited glioma cell proliferation ability and cell cycle progression via targeting CCNE1 and the miR-588/TUSC1 axis." (PMID 35795204, 2022). "Chromatin Immunoprecipitation (ChIP) assays were conducted to test whether the CBX7 could bind to the CCNE1 promoter in glioma cells." (PMID 28460453, 2017). "Importantly, these results also suggest that NF-κB pathway is critical for URGCP-induced Cyclin D1 and Cyclin E1 expression in glioma." (PMID 29044221, 2017). "To investigate whether NF-κB pathway is involved in URGCP-increased Cyclin D1 and Cyclin E1 expression in glioma, we performed western blotting." (PMID 29044221, 2017). "Indeed, we found positive correlations between URGCP and Cyclin D1 and Cyclin E1 expression in glioma tissues." (PMID 29044221, 2017). "Moreover, we show that miR-195 inhibited glioma cell proliferation by downregulating expression of cyclin D1 and cyclin E1, via directly targeting the 3′-untranslated regions (3′-UTR) of cyclin D1 and cyclin E1 mRNA." (PMID 23383003, 2013). "Therefore, we asked whether miR-16 is involved in URGCP-induced Cyclin D1 and Cyclin E1 expression in glioma." (PMID 29044221, 2017). "In addition, we identified Cyclin D1 and Cyclin E1 as direct targets of miR-16 in glioma cells, overexpressing miR-16 significantly decreased Cyclin D1 and Cyclin E1 expression in glioma cells, suggesting that miR-16 is involved in URGCP-enhanced Cyclin D1 and Cyclin E1 expression in glioma." (PMID 29044221, 2017). "However, despite its role as an oncogene, only recently it has been proposed in human glioma cells a mechanism for the regulation of CCNE1 activity that involves the miR-195 and leads to the reduction of pRb phosphorylation and to the downregulation of the proliferative marker PCNA." (PMID 26880947, 2016). "Importantly, co-expression of Cyclin D1 and Cyclin E1 indeed could further potentiate the proliferation of glioma cells, compared to that of Cyclin D1 or Cyclin E1 expressed alone." (PMID 23383003, 2013). "MiR-15b could regulate cell cycle progression in glioma cells by targeting cyclin E1." (PMID 22723898, 2012).